RNU4-54P (RNA, U4 small nuclear 54, pseudogene)
Gene: Small nuclear RNA gene on chromosome 12 (28,319,335 to 28,319,463, reverse strand). Ensembl gene ENSG00000252237.
Homologues: Orthologues: chimpanzee U4 (98% identical), rabbit U4 (57% identical), tropical clawed frog U4 (51% identical), tropical clawed frog U4 (50% identical), tropical clawed frog U4 (47% identical). Paralogues in human: RNU4-4P (57% identical), RNU4-48P (56% identical), RNU4-82P (56% identical), RNU4-39P (54% identical), RNU4-57P (54% identical), RNU4-6P (53% identical), RNU4-55P (53% identical), RNU4-53P (52% identical), RNU4-79P (52% identical), U4 (52% identical), RNU4-9P (51% identical), RNU4-12P (50% identical), and 82 more.